RN7SL424P (RNA, 7SL, cytoplasmic 424, pseudogene)
Gene: Miscellaneous RNA gene on chromosome 4 (55,063,738 to 55,064,026, forward strand). Ensembl gene ENSG00000244034.
Homologues: Orthologues: chimpanzee Metazoa_SRP (99% identical), macaque Metazoa_SRP (92% identical). Paralogues in human: RN7SL2 (79% identical), RN7SL45P (79% identical), RN7SL1 (79% identical), RN7SL3 (77% identical), RN7SL126P (77% identical), RN7SL448P (77% identical), RN7SL543P (76% identical), RN7SL836P (76% identical), RN7SL88P (76% identical), RN7SL230P (76% identical), RN7SL665P (76% identical), RN7SL709P (76% identical), and 703 more.